BDNF (brain derived neurotrophic factor)
Diseases named in the same sentence as BDNF in open-access papers (continued):
Sharing a sentence is not in itself a finding about the gene and the disease.
diabetes (continued). "Recently, RSG formulated with nanoparticles was shown to modulate BDNF and its upstream signaling pathway substrates in models of diabetes and AD." (PMID 37508471, 2023). "In a model with BDNF as a potential mediator, we found that total and direct effects of diabetes on MoCA were significant for PreDM and T2DM (p<0.05)." (PMID 36936159, 2023). "Consistent with other studies, a recent experimental investigation revealed significant dysregulation in the expression and density of BDNF in the hippocampus of offspring exposed to diabetes during critical periods of neurodevelopment." (PMID 37469977, 2023). "Activation of the BDNF/TrkB/CREB reduces hepatic gluconeogenesis, induces hepatic insulin signal transduction, and protects against pancreatic beta-cell loss in diabetes mellitus (DM)." (PMID 36787304, 2023). "Mice with diabetes given empagliflozin or dapagliflozin showed a significant increase in BDNF and NT4 protein levels in the prefrontal cortex." (PMID 36869919, 2023). "FTS⋅B can also increase the expression of BDNF and inhibit the expression of inflammatory factors, thereby restoring the cognitive function of postmenopausal diabetes." (PMID 36389075, 2022). "Diabetes patients’ blood levels of BDNF were significantly lower than healthy controls, and this depletion was mediated by diabetes-induced chronic hyperglycemia and AGE accumulation." (PMID 35682821, 2022). "In the present study, we identified an interaction effect of diabetes and a low sBDNF level or the BDNF Met/Met genotype on acute SI in ACS patients." (PMID 35459929, 2022). "It is the first prospective study to evaluate the interaction effects of diabetes and the BDNF pathway on SI." (PMID 35459929, 2022). "On the other hand, some genes such as PPAR‐γ, LXRs, and BDNF have been shown beneficial effects on glucose metabolism and diabetes." (PMID 36200185, 2022). "It is noteworthy that interaction effects between diabetes and a low sBDNF level or the BDNF Met/Met genotype on SI were significant during the first 2 weeks but not at 1 year after an ACS episode." (PMID 35459929, 2022). "The low expression of BDNF in db/db mice is consistent with the results of previous studies of other mouse models of diabetes." (PMID 36091357, 2022). "Baseline diabetes and the high vs. low sBDNF level or BDNF Val/Val vs. Met/Met genotype showed multiplicative interactions in their associations with acute SI among patients with ACS." (PMID 35459929, 2022). "Another study has shown that harmine administration rose the levels of BDNF, as well as p-TrkB in both the high glucose-treated cells and the diabetic rats, and ameliorated cognitive dysfunction induced by diabetes." (PMID 36455873, 2022). "A synergistic effect between diabetes and a low sBDNF level or the BDNF Met/Met genotype in our cohort is biologically plausible." (PMID 35459929, 2022). "To determine if MCs are the cellular target for the regulation of BDNF production in diabetes, we examined the synthesis of BDNF in rMC1 cells." (PMID 34068807, 2021). "Results showed that AChE and BDNF levels were significantly decreased in SMG of the untreated diabetes rats compared to the control group." (PMID 34987398, 2021). "We showed previously that diabetes downregulated retinal BDNF accumulation, and disruption of VEGFR2 in Müller glia caused an accelerated loss of retinal BDNF in diabetic mice." (PMID 34068807, 2021). "Several clinical studies paid attention to the association of circulating BDNF in either plasma or serum with CVD, including coronary artery disease, angina, HF, and diabetes." (PMID 33477900, 2021). "BDNF also improves insulin resistance and lipid metabolism through the upregulation of energy metabolism in a mouse model of diabetes mellitus." (PMID 34440543, 2021). "Our results provide direct evidence that VEGF is a positive regulator for BDNF production in diabetes for the first time." (PMID 34068807, 2021).
diabetes (continued). "In our hands, VEGF played a prominent role in promoting MC survival and proliferation, which led to an increase of MC-mediated BDNF production under diabetes-like conditions." (PMID 34068807, 2021). "BDNF has been found to be a promising agent against DR; intravitreal injections of BDNF rescued dopaminergic ACs in induced diabetes." (PMID 35095518, 2021). "ELISA analysis of culture supernatants from rMC1 cells indicated that, while diabetes-like conditions (HG) significantly downregulated BDNF production, rVEGF stimulated the BDNF secretion in a dose-dependent manner (NG)." (PMID 34068807, 2021). "From in vivo studies, osthole (20 mg/kg per day for 14 days) reduced the up-regulation of the P2X4 receptor, and downregulated the IL-1β, TNF-α, brain-derived neurotrophic factor, and p-p38MAPK and upregulated IL-10 in diabetes mellitus." (PMID 32028721, 2020). "The study explained the properties of exogenous BDNF in animals with streptozotocin-induced diabetic neuropathic pain." (PMID 32012942, 2020). "FGF1 effectively blocks diabetes-induced neuronal apoptosis and BDNF reduction, consequently ameliorates DICD though inhibiting PERK signaling and promoting PI3K/AKT signaling." (PMID 32460803, 2020). "It is helpful that the recommendations for DR mirror those for diabetes and macular degeneration generally, and for reducing Hcy, hypertension, and increasing BDNF and other nerve growth neurotropic factors so that many benefits flow from similar treatments." (PMID 32582807, 2020). "In this study, we found that diabetes obviously suppressed the expressions of BDNF and MAP 2 in the hippocampus when comparing with those in db/m mice, and which were abolished by FGF1 administration." (PMID 32460803, 2020). "Different antioxidant compounds have been investigated for their possible favorable effects on the BDNF level in diabetes." (PMID 32405353, 2020). "BDNF is higher in prediabetic patients than in diabetic patients, suggesting neuroprotective benefits for patients with insulin resistance and pre-diabetes." (PMID 32582807, 2020). "On the other hand, very limited studies have shown the relation of lncRNAs with BDNF in neurodegenerative disease and diabetes, which are mainly in vitro and in vivo analysis." (PMID 33374507, 2020). "Previous studies have shown that BDNF/TrkB signaling is involved in the progression of diabetes-induced cognitive dysfunction." (PMID 32425784, 2020). "They concluded that patients with type 2 diabetes mellitus during the eight-week neuromuscular electrical stimulation training program had greater changes in BDNF plasma levels than the control intervention." (PMID 32012942, 2020). "Serum levels of BDNF in the control group were higher compared to the patients with diabetes mellitus type 2." (PMID 32012942, 2020). "According to published reports, it seems that diabetes decreases BDNF levels by increasing oxidative stress or by other independent mechanisms of oxidative stress." (PMID 32405353, 2020). "Apart from VEGF, another important growth factor, which is involved in both neurodegenerative disease and diabetes, is BDNF." (PMID 33374507, 2020). "Circulating concentrations of brain-derived neurotrophic factor (BDNF) have been linked to cancer, neuropsychiatric, diabetes, and gynecological disorders." (PMID 33214644, 2020). "In patients with diabetes, the authors also showed correlations between BDNF concentration and BMI, percentage of body fat, subcutaneous fat area based on CT (computed tomography) scan, triglyceride level in serum, fasting glucose level, and HOMA-IR." (PMID 32012942, 2020). "Studies are not only limited to in vitro and in vivo analysis, but several human studies were also conducted regarding BDNF-miRNAs interaction in diabetes, AD, PD, HD, multiple sclerosis and ischemic stroke." (PMID 33374507, 2020).
diabetes (continued). "Studies show that diabetes reduces the concentration of BDNF in the central nervous systems of animals, and this phenomenon can be reversed through endurance training." (PMID 32012942, 2020). "During their study, they proved that adolescents with type 2 diabetes mellitus and a control group had similar resting BDNF levels." (PMID 32012942, 2020). "There was a strong, positive correlation between BDNF and glucose disposal rate and a significant relationship between clamp results and BDNF, adjusted for sex, duration of diabetes and mean HbA1c." (PMID 32012942, 2020). "The same observations were seen in a Chinese population: BDNF serum levels in patients with type 2 diabetes mellitus were significantly lower than in a healthy control group." (PMID 32012942, 2020). "The level and function of BDNF in diabetes seems to be disturbed by and connected with the presence of insulin resistance." (PMID 32012942, 2020). "The purpose of this review article is to explore the connection between brain-derived neurotrophic factor (BDNF) and diabetes." (PMID 32012942, 2020). "BDNF decreased food intake, increased energy expenditure and reversed hyperinsulinemia and ameliorated type 2 diabetes mellitus in experimental animals." (PMID 31823816, 2019). "Our results further corroborate the finding that BDNF is sufficient to reduce neuroinflammation, providing another therapeutic target to treat brain injury in diabetes." (PMID 31165005, 2019). "In the present study, we aimed to investigate the effects of BDNF overexpression in the hippocampus on mitigating synaptic impairments and reducing neuroinflammation in mice with diabetes induced by STZ." (PMID 31165005, 2019). "BDNF levels have been related to a variety of somatic diseases, including inflammatory diseases, diabetes mellitus, cardiovascular diseases and asthma." (PMID 31127089, 2019). "STZ (65 mg/kg)-induced type 2 diabetes mellitus animals showed reduced plasma BDNF and LXA4 levels (P < 0.001)." (PMID 31823816, 2019). "This lends support to the concept that a deficiency of BDNF and LXA4 play a significant role in the development of diabetes mellitus." (PMID 31823816, 2019). "The results of the present study suggest that BDNF, LXA4, EPA, DHA, AA, GLA and BDNF protect pancreatic β cells from the cytotoxic action of various chemicals and prevent development of diabetes mellitus." (PMID 31823816, 2019). "In different layers of colon wall, the expressions of AGE, RAGE, TGF-β1 and TGF- β receptor were stronger whereas BDNF and TrkB expressions were weaker in the Diabetes group than in Control group." (PMID 29930382, 2018). "Lower BDNF concentrations have been associated with known risk factors for CAD including lipid levels, elderly age, male gender, smoking, diabetes mellitus, and physical inactivity." (PMID 29409455, 2018). "As our cohort shows a typical frequency distribution of nephropathies with the largest proportion suffering from diabetes, which is one of the major causes of CKD, we investigated the expression of BDNF and KIM‐1 in diabetic and non‐diabetic patients." (PMID 30133147, 2018). "Low BDNF levels were associated with increased LDL levels and the presence of diabetes mellitus, similar to another study." (PMID 29409455, 2018). "Future studies are needed to investigate how diabetes induces abnormal expressions of BDNF and TrkB in GI tract." (PMID 29930382, 2018). "Present study aims to investigate the role of AGEs, TGF-β1, BDNF and their receptors on diabetes-induced colon remodeling." (PMID 29930382, 2018). "Univariate logistic analyses revealed that age, male sex, hypertension, diabetes mellitus, triglycerides, HDL cholesterol, BDNF and vWF were significantly associated with the presence of stable CAD." (PMID 29409455, 2018). "High vWF levels were associated with low BDNF levels even after adjustment for age, gender, low-density lipoprotein (LDL) levels, and the presence of diabetes mellitus." (PMID 29409455, 2018).
diabetes (continued). "We have provided novel data indicating that COX-2 and BDNF/TrkB signaling pathways are pathological and therapeutic targets for memory deficits in a rat model of diabetes." (PMID 28466254, 2017). "Retinal levels of BDNF are reduced in animal models of streptozotocin-induced diabetes, and this reduction of BDNF is correlated with amacrine cell degeneration." (PMID 29062839, 2017). "We measured the protein levels of hippocampal BDNF and TrkB in the rat and found that BDNF level in the hippocampal homogenate was markedly downregulated in the diabetes model group." (PMID 28466254, 2017). "The current study demonstrated celecoxib reversed the decrease in the expression of hippocampal BDNF-TrkB in a rat model of diabetes." (PMID 28466254, 2017). "Since the validity of the assay system was guaranteed, the effects of high glucose, mannitol and AGE on BDNF release from platelets were examined because hyperglycemia is the primary manifestation of diabetes." (PMID 28178976, 2017). "We further revealed that celecoxib reversed the damage in hippocampal BDNF-TrkB signaling pathway in a rat model of diabetes." (PMID 28466254, 2017). "Diabetes also decreases the anterograde and retrograde axonal transport of BDNF, NGF, and NT-3 in peripheral nerves." (PMID 28900628, 2017). "In pathological conditions, for example in atherosclerosis and diabetes, vascular cells seem to express the pro-BDNF receptor p75NTR promoting cell apoptosis and inhibiting angiogenesis, which may be another explanation for the high BDNF levels observed in subjects with a high cardiovascular risk." (PMID 29028824, 2017). "In this model of diabetes, the impaired cognitive ability was evaluated by Morris water maze and decreased synaptic plasticity was monitored via examining the expression of brain derived neurotrophic factor (BDNF) and N-methyl-D-aspartate receptor (NMDAR1)." (PMID 29209211, 2017). "They consumed more alcohol, had higher BP and mean pre-diabetes (HbA1c) levels, lower BDNF levels (p < 0.001), larger cortisol:BDNF ratios (p = 0.012) and a higher mean 24-hour hypertensive state." (PMID 27966001, 2016). "In this sense, we have previously shown that EE avoided the decrease in retinal BDNF levels at early stages of experimental diabetes." (PMID 26312758, 2015). "For the first time, current study suggests a cut-off point for serum BDNF of type 2 diabetes mellitus." (PMID 25587547, 2014). "Among lifestyle measures, diabetes and current smoking showed significant differences between the participants who had high and low serum BDNF levels." (PMID 24782766, 2014). "Patients who had a serum BDNF level more than 137 pg/mL were a predictive value like HbA1c for the diabetes diagnosis with a sensitivity of 71.79% and a specificity of 68%." (PMID 25587547, 2014). "The aim of this study was to evaluate the relationship between serum BDNF levels and various metabolic parameters and inflammatory markers in patients with type 2 diabetes mellitus (T2DM).Materials and Methods." (PMID 25587547, 2014). "BDNF has been reported to influence fasting GLU levels and insulin sensitivity, and decreased levels of the serum BDNF were found in the patients with MetS and type 2 diabetes mellitus." (PMID 23967328, 2013). "BDNF protein levels in the retinas of animals with diabetes (0.03 ± 0.01 pg/μg protein) were significantly lower than those in nondiabetic controls (0.06 ± 0.02 pg/μg protein) (P = 0.014; Mann-Whitney U test)." (PMID 23766563, 2013). "Constant GA intake from the onset of diabetes significantly attenuated diabetes-induced downregulation of BDNF (P = 0.048)." (PMID 23766563, 2013). "Western blot analysis was used to assess the effect of GA on diabetes-induced alterations of BDNF in the retinas of rats." (PMID 23766563, 2013). "The effect of the HMGB1 inhibitor glycyrrhizin on diabetes-induced changes in retinal BDNF expressions was studied." (PMID 23766563, 2013).
diabetes (continued). "On the other hand, diabetes induced significant downregulation of the neurotrophin BDNF, the synaptic function marker synaptophysin, and GS." (PMID 24347828, 2013). "We found that PARP inhibition by 1,5-isoquinolinediol significantly prevented the diabetes-induced downregulation in BDNF, synaptophysin, and GS and upregulation of cleaved caspase-3 expressions." (PMID 24347828, 2013). "Recent studies suggested that the early retinal neuropathy of diabetes involves the reduced expression of BDNF and can be ameliorated by an exogenous supply of this neurotrophin." (PMID 23766563, 2013). "Our findings suggest that diabetes-induced decrease of BDNF in the retina seems to be mediated by HMGB1." (PMID 23766563, 2013). "In conclusion, these data suggest that PARP activation mediates diabetes-induced increased oxidative stress, downregulation of BDNF, synaptophysin, and GS, and upregulation of caspase-3." (PMID 24347828, 2013). "In conclusion, these data suggest that diabetes-induced increased oxidative stress, downregulation of BDNF and synaptophysin, and upregulation of cleaved caspase-3 were also induced by HMGB1." (PMID 23766563, 2013). "Therapeutic potential of the combination of BDNF with the drug enhancing insulin secretion against diabetes should be investigated in future study." (PMID 24106476, 2013). "Studies on muscle damage in chemically induced diabetes models show impaired recovery, while this interesting link between diabetes, BDNF and muscle recovery remains to be studied in humans." (PMID 20353613, 2010). "Disrupted muscle repair would be consistent with the involvement of BDNF expression inhibiting myogenesis and we demonstrated that BDNF is elevated in proliferating satellite cells from diabetes patients." (PMID 20353613, 2010). "Further studies have shown that BDNF levels are an important predictor of diabetes." (PMID 40933306, 2025). "Future longitudinal studies incorporating oral glucose tolerance test (OFTT) screening and serial renal assessments are warranted to reduce misclassification bias and better delineate the interplay between BDNF, micronutrients, inflammation, and kidney function in diabetes." (PMID 41142318, 2025). "Gao observed a significant decrease in the expression of synaptic-related proteins such as c-fos, Synapsin1, Synaptotagmin1, and BDNF in both mouse diabetes models and in vitro cultured hippocampal neuronal cell models, and melatonin can reverse the imbalance of these protein expressions." (PMID 41300164, 2025). "In older adults with type T2DM, a longer duration of diabetes is linked to lower BDNF levels, indicating a negative correlation." (PMID 40933306, 2025). "This may be due to the consumption or downregulation of BDNF in platelets being induced during the progression of diabetes." (PMID 41280373, 2025). "In diabetes, ensuring zinc sufficiency might help preserve BDNF activity and mitigate neuropathic changes." (PMID 41142318, 2025). "The findings reinforce the concept that better nutritional and inflammatory management may preserve BDNF and protect patients, a holistic approach that could slow the vicious cycle of diabetes and its complications." (PMID 41142318, 2025). "Although several reports have examined serum BDNF in diabetes, few have systematically explored its relationships with vitamins D, B12, and folic acid, trace elements (zinc, calcium), and pro-inflammatory cytokines (IL-6, IL-12) in the context of diabetic nephropathy." (PMID 41142318, 2025). "The evidence suggests that diabetes negatively impacts BDNF levels among the elderly." (PMID 40933306, 2025). "It is of importance that cerebral endothelial BDNF expression is reduced in animal models of hypertension, diabetes, and rheumatoid arthritis, indicating that diminished endothelial BDNF expression could be a novel marker of endothelial dysfunction." (PMID 38338875, 2024).